IL32 (interleukin 32)
Diseases named in the same sentence as IL32 in open-access papers (continued):
Sharing a sentence is not in itself a finding about the gene and the disease.
heart failure (3 papers, 2025 to 2026). Inability of the heart to pump blood at an adequate rate to meet tissue metabolic requirements. "Furthermore, IL-32 is expressed by PBMC of patients with heart failure and seric IL-32 concentrations have been positively correlated with cardiac fibrosis and poor outcomes after myocardial infarction, strongly suggesting its contribution to cardiac remodeling, through NFκB activation." (PMID 39934117, 2025).
HIV-1 infection (3 papers, 2012 to 2021). The type species of lentivirus and the etiologic agent of acquired immunodeficiency syndrome (AIDS). "In HIV-1 infection, IL-32 inhibits antiviral immune response and therefore supports HIV-1 replication, resulting in viral persistence." (PMID 34712431, 2021). "On the other hand, depletion of endogenous IL-32 in HIV-1 infection resulted in down-regulation of proinflammatory cytokines and increased HIV-1 production." (PMID 34712431, 2021). "Interestingly, there is a good correlation between IL-32 levels and HIV-1 replication in lymphatic tissues and IL-32 was recently shown to play an immunosuppressive role in lymphatic tissues during HIV-1 infection." (PMID 22624040, 2012). "Moreover, to further characterize the relation between miRNA-29b and IL-32 expression, we investigated whether miRNA-29 levels influence the amount of IL-32 and MxA during HIV-1 infection." (PMID 25808800, 2015).
leukemia (3 papers, 2012 to 2019). A malignant (clonal) hematologic disorder, involving hematopoietic stem cells and characterized by the presence of primitive or atypical myeloid or lymphoid cells in the bone marrow and the blood. "For reference, we also evaluated IL32 transcript levels in the Jurkat T cell line, a recognized high IL32 expressing leukemia cell line." (PMID 30953519, 2019). "IL32 is also expressed in a broad range of human epithelial cancers–gastric, lung, breast, colon, pancreas, and thyroid —as well as hematologic malignancies such as lymphoma and leukemia." (PMID 30953519, 2019). "Herein, we showed that IL-32 has a role in stromal cell crosstalk with leukemia cells, and that TNF-α must be part of this network, at least in vitro, since the protection from AraC-induced apoptosis conferred by HS5 miIL32 was reversed upon the addition of TNF-α." (PMID 28084439, 2017). "In addition, LPS and phorbol myristate acetate induced IL-32 expression in a leukemia cell line and in endothelial cells." (PMID 22413812, 2012). "Furthermore, data indicate that IL-32 regulates stromal cell proliferation, has a chemotactic potential and participates in stromal cell crosstalk with leukemia cells, which could result in chemoresistance." (PMID 28084439, 2017).
lung injury (3 papers, 2015 to 2024). "Our previous studies also showed that IL-32 inhibited NF-κB and STAT3 in tumor growth models as well as acetoaminophen-induced liver injury and 1-methyl-4-phenyl-1,2,3,6-tetrahydropyridine induced Parkinson models (data not shown)." (PMID 26497686, 2015).
metastatic disease (3 papers, 2009 to 2026). "We identified a new cluster of IL32 + B cells (BC2) that are CD38-SDC1-S100A4+GAPDH+; these cells were found in both primary and metastatic tumor sites with high T cell infiltration, deriving primarily in clear cells and SOC histotypes." (PMID 38328306, 2023).
metastatic melanoma (3 papers, 2007 to 2020). A melanoma that has spread from its primary site to another anatomic site. "In summary, this study shows that a significant percentage of cell lines derived from metastatic melanoma express IL32." (PMID 30953519, 2019). "Moreover, we recently observed NK4/IL-32 to be preferentially expressed in metastatic melanoma compared with other less immune responsive cancers." (PMID 17222352, 2007).
myocardial infarction (3 papers, 2023 to 2026). Gross necrosis of the myocardium, as a result of interruption of the blood supply to the area, as in coronary thrombosis. "On the other hand, IL-32 was recently reported to be upregulated in HF, with higher levels of IL-32 upon initial myocardial infarction predicting lower probability of HF-free status for a period of 2 years." (PMID 36992409, 2023).
nasal polyps (3 papers, 2016 to 2023). "Further studies are required to assess the role of IL-32 in nasal polyps in patients with chronic rhinosinusitis." (PMID 29564208, 2018). "IL-32-positive inflammatory cells were found to be elevated in nasal polyps as well." (PMID 27143819, 2016). "Colocalization of IL-32 with CD68+ macrophages and CD3+ T-cells was confirmed through immunofluorescence studies which was a clear indicative of positive correlation of its expression with CD3 and macrophage mannose receptor in nasal polyps." (PMID 27143819, 2016). "Presence of IL-32 was reported in some glandular tissues of nasal polyps using immunofluorescent staining though its source was not confirmed as to whether it was coming from unfiltered inflammatory cells or from glandular epithelium." (PMID 27143819, 2016).
non-alcoholic fatty liver disease (3 papers, 2022 to 2025). "Elevated circulating IL-32 levels have been reported in individuals with non-alcoholic fatty liver disease and hepatitis B virus infection compared to healthy controls." (PMID 40149726, 2025).
Pleural effusion (3 papers, 2015 to 2024). The presence of an excessive amount of fluid in the pleural cavity. "IL-32 levels were evaluated in the pleural effusions of 131 patients with undetermined pleural effusion from Wuhan and Beijing cohorts using an enzyme-linked immunosorbent assay method." (PMID 35880892, 2022). "Our data support IL-32 in pleural effusion as a biomarker with diagnostic value in TPE." (PMID 35880892, 2022). "Therefore, the diagnostic accuracy of IL-32 in pleural effusion and the multivariate model for TPE diagnosis needs to be further verified in subsequent concurrent multicenter cross-sectional studies." (PMID 35880892, 2022). "TPE had a higher level of IL-32 compared with the MPE and transudative pleural effusion, indicating the unique role of IL-32 in the process of occurrence and development of TB." (PMID 38803498, 2024). "Mononuclear cells in 23 human pleural effusion samples were investigated for total IL-32, IL-32 isoforms (IL-32α, IL-32β, and IL-32γ), and ADA2 mRNA expression, and correlation studies were performed." (PMID 35880892, 2022). "We demonstrate that a high IL-32 level in the pleural effusion is a valuable biomarker for identifying patients with TPE." (PMID 35880892, 2022). "This study indicates that interleukin 32 (IL-32) in pleural effusion is a new high-potency marker to distinguish TPE from pleural effusions with other etiologies." (PMID 35880892, 2022). "Third, the content of IL-32 detected locally in TPE is higher than that in other pleural effusions, which may be attributed to the stimulation of local Mtb in TPE." (PMID 38803498, 2024). "Our results indicate that IL-32 in pleural effusion may be a novel biomarker for identifying patients with TPE." (PMID 35880892, 2022). "The average concentrations of IL-32 in TPE were significantly higher than in MPE and transudative pleural effusion (such as the history of heart disease) (all p < 0.05)." (PMID 38803498, 2024). "The positive likelihood ratio (PLR) value of 13.5 for IL-32, which suggests that patients with IL-32-positive pleural effusion have a 13.5-fold-higher chance of having TPE than non-TPE, is sufficient to include patients." (PMID 35880892, 2022). "The correlations between IL-32 in pleural effusion and cytological or biochemical parameters of TPE and non-TPE were determined." (PMID 35880892, 2022). "The level of IL-32 was positively correlated with ADA, LDH, and nucleated cell counts, generally related to total protein in pleural effusions (all P < 0.001), and negatively correlated with glucose (P < 0.05) but was not correlated with the mononuclear cell ratio (P > 0.05)." (PMID 35880892, 2022). "Furthermore, the IL-32 expressions in the TPE, MPE, and transudative pleural effusion were checked." (PMID 38803498, 2024).
pulmonary tuberculosis (3 papers, 2016 to 2024). A bacterial infection that affects the lungs and is caused by Mycobacterium tuberculosis. "For example, IL-32 is linked to the balance of Th1/Th17 cytokines in the peripheral blood of patients with pulmonary tuberculosis and high levels of IFN-γ and TNF-α expression in T cells in lung tissue of IL-32γ-transgenic mice infected with Mtb." (PMID 38803498, 2024). "The study analyzed the levels of IL-32 mRNA in active pulmonary tuberculosis, latent pulmonary tuberculosis, healthy individuals, and other diseases." (PMID 38803498, 2024). "Results showed that IL-32 mRNA expression was higher in latent tuberculosis patients compared to that in active pulmonary tuberculosis and healthy individuals." (PMID 38803498, 2024). "Herein, we observed that the level of total IL-32 mRNA in the whole blood of patients with pulmonary tuberculosis decreased compared with that in patients with latent tuberculosis infection and healthy controls, indicating its possible role in congenital prevention of Mtb infection." (PMID 38803498, 2024). "IL-32, a novel pleiotropic cytokine capable of inducing pro-inflammatory cytokines such as TNF-α and IL-1β and elevated in the sera of active pulmonary TB, can be triggered by IL-12." (PMID 27634911, 2016).
renal cell carcinoma (3 papers, 2017 to 2024). "In renal cell carcinoma, a previous study showed that IL-32 overexpression was associated with high recurrence rates, low recurrence free survival and overall survival, and thus may be a new prognostic factor." (PMID 29190960, 2017).
stomach cancer (3 papers, 2016 to 2020). "Tumors of gastric cardia (n = 5) tended to have higher concentration of IL-32 than non-cardia tumors (n = 7) by 2.0-fold (p = 0.169), accompanied by slightly lower abundance in non-adjacent tissue (by 1.3-fold, p = 0.565)." (PMID 33020452, 2020). "Gastric tumors had IL32 expression higher than colorectal tumors by 2.1-fold." (PMID 33020452, 2020).
vasculitis (3 papers, 2018 to 2022). "Increased IL-32 expression and serum levels has been reported in patients of GCA and Anti-Neutrophilic Cytoplasmic Autoantibody (ANCA) associated vasculitis." (PMID 35813204, 2022). "This study revealed the effects of LA on endothelial cell activation, NLRP3, IL-1β, TNF-α, IL-32, and CCL-2, VCAM-1, MCP-1, and the spleen tyrosine kinase (Syk)--p38/JNK signaling axis and its effect on vasculitis in rats." (PMID 30158835, 2018).
acute-on-chronic liver failure (2 papers, 2015 to 2018). Acute-on-chronic liver failure (ACLF) is an extreme condition during the natural history of chronic HBV infection, with a relatively high short-term mortality. "It has been demonstrated that NKp30-B7-H6 interaction can aggravate hepatocyte damage through up-regulation of interleukin-32 in HBV-related acute-on-chronic liver failure." (PMID 30186042, 2018).
Alzheimer disease (2 papers, 2023 to 2025). A progressive, neurodegenerative disease characterized by loss of function and death of nerve cells in several areas of the brain leading to loss of cognitive function such as memory and language. "Similarly, we found that genetic liability to Alzheimer’s disease had causal effects on levels of APOF (p = 2.4*10−07), and IL32 (p = 7*10−11)." (PMID 40281223, 2025).
cervical cancer (2 papers, 2015 to 2017). A primary or metastatic malignant neoplasm involving the cervix. "IL-32 expression was elevated in cervical cancer tissues and human papilloma virus (HPV)-positive cervical cancer cells." (PMID 26087456, 2015).
chronic hepatitis C (2 papers, 2020 to 2025). "CD4P/I(hi) T cells also expressed several genes not typical of the Tfh subset, including EBI3, a subunit of the IL-27, IL-35, and IL-39 cytokines, and the inflammatory cytokine IL32 associated with liver injury in chronic hepatitis C." (PMID 40956619, 2025). "Clearance of HCV core protein or modulation of IL-32 activity might be an option to reduce inflammation in patients with chronic hepatitis C." (PMID 32373543, 2020).
chronic viral hepatitis (2 papers, 2014 to 2020). "Since IL-32 exerts pro-inflammatory effects in various cell types including epithelial, endothelial, and mononuclear cells, our results might explain the important role of HCV core protein in developing viral hepatitis." (PMID 32373543, 2020).
Cirrhosis (2 papers, 2023 to 2025). A chronic disorder of the liver in which liver tissue becomes scarred and is partially replaced by regenerative nodules and fibrotic tissue resulting in loss of liver function. "Although a number of inflammatory cytokines and chemokines were differentially expressed in PoPH nuclei as compared to non-PoPH cirrhosis nuclei across multiple clusters, the strongest associations were for increased IL6R and IL4R expression and decreased IL32 expression in PoPH clusters." (PMID 37558836, 2023).
esophageal cancer (2 papers, 2022 to 2024). A primary or metastatic malignant neoplasm involving the esophagus. "The plasma expression levels of IL-32 in patients with malignant esophageal cancer increased, promoting the progression of esophageal cancer through the activation of NF-κB and the increased levels of cytokines TNF-α, IL-6, and IL-1β40." (PMID 38584169, 2024).
esophageal tumors (2 papers, 2020). "Pairwise analysis showed that IL32 expression is significantly upregulated (by 3.3-fold) solely in esophageal tumors." (PMID 33020452, 2020).
fibrosis (2 papers, 2018 to 2023). the formation of excess fibrous connective tissue in an organ or tissue in a reparative or reactive process. "In the present study, we analyzed the expression of liver injury-related genes in patients with MASLD and could demonstrate a significant upregulation of IL-32 and CCL20 in MASH samples with progressed activity (intense steatosis and moderate-to-severe fibrosis)." (PMID 37686029, 2023).
giant cell arteritis (2 papers, 2021 to 2023). "Besides, increased IL32 was found in giant cell arteritis with enhanced B-cell survival and expansion." (PMID 34658852, 2021).
head and neck squamous cell carcinoma (2 papers, 2020 to 2025). A squamous cell carcinoma that arises from any of the following anatomic sites: lip and oral cavity, nasal cavity, paranasal sinuses, pharynx, larynx, and salivary glands. "This suggests that IL32+NK cells may play a crucial role in immune surveillance and regulation within the immune microenvironment of head and neck squamous cell carcinoma." (PMID 41181127, 2025).
Hepatitis (2 papers, 2020 to 2023). Inflammation of the liver. "Among those mRNA transcripts, IL-32 was considered the most important factor leading to hepatitis in infected marmosets." (PMID 32373543, 2020). "In conclusion, HCV core protein induces an increase of IL-32 expression via the PI3K pathway in hepatic cells, which played a major role in development of HCV-related severe hepatitis." (PMID 32373543, 2020).
hepatitis B (2 papers, 2024 to 2025). "Besides, based on the ARCHS4 database, IL-32 was predicted to be involved in hepatitis B, cytokine–cytokine receptor interaction, and viral carcinogenesis pathways." (PMID 38587834, 2024).
hepatitis C infection (2 papers, 2024 to 2025). "In patients with hepatitis C infection, hepatic IL-32 mRNA expression has been positively correlated with inflammation, fibrosis scores, and serum alanine aminotransferase levels." (PMID 40149726, 2025).
inflammatory skin disease (2 papers, 2016 to 2023). Inflammatory skin disorders covers a broad category that includes many conditions ranging in severity, from mild itching to grave medical health complications These disorders are common in people of all ages and races. "This review highlights that IL-32, particularly IL-32α, β, and γ, also play a pro-inflammatory role in the pathogenesis of various inflammatory skin disorders." (PMID 37727785, 2023). "In conclusion, IL-32 is elevated locally and systemically in various inflammatory skin disorders and decreases with anti-inflammatory therapies in AD and AA, leading to improvement in disease symptoms." (PMID 37727785, 2023). "Among these cytokines, IL-32 produced by keratinocytes has been shown to increase KC apoptosis in inflammatory skin diseases." (PMID 27528123, 2016). "Therefore, this review focuses on the biological functions of IL-32, particularly in AD and other inflammatory skin disorders, and evaluates its potential as a biomarker and therapeutic target in these diseases." (PMID 37727785, 2023).
influenza (2 papers, 2012). An acute viral infection of the respiratory tract, occurring in isolated cases, in epidemics, or in pandemics; it is caused by serologically different strains of viruses (influenzaviruses) designated A, B, and C, has a 3-day incubation period, and usually lasts for 3 to 10 days. "Several previous reports have indicated that IL-32 expression was upregulated by Mycobacterium tuberculosis infection or LPS in peripheral blood mononuclear cells and was also upregulated by influenza and HIV virus infection in the A549 and HEK293T human embryonic kidney cell lines, respectively." (PMID 22413812, 2012). "IL-32 plays an important role in host defense against microorganisms including Mycobacterium, HIV, and influenza." (PMID 23190696, 2012).
liver cirrhosis (2 papers, 2022 to 2025). "Liver cirrhosis is associated with increased mortality risk, but the potential role of IL-32 in this context is yet to be determined." (PMID 40149726, 2025). "This reduction became statistically significant only after excluding patients with liver cirrhosis, with increased systemic IL-32 concentrations." (PMID 40149726, 2025). "In septic patients with liver cirrhosis, plasma IL-32 concentrations were increased." (PMID 40149726, 2025). "Interestingly, serum IL-32 is gradually increased from the cohorts of the control, acute hepatitis, chronic hepatitis, liver cirrhosis, and HCC, further linking IL-32 and its pro-inflammatory effects with the severity and duration of hepatic damage." (PMID 36438052, 2022). "The cellular source of elevated plasma IL-32 in liver cirrhosis remains unclear." (PMID 40149726, 2025). "The positive correlation between IL-32 and markers of liver injury—such as bilirubin, gamma-glutamyl transferase, and aminotransferases—in patients without liver cirrhosis suggests that the association between IL-32 expression and liver damage extends to critical illness." (PMID 40149726, 2025).
lymphoma (2 papers, 2016 to 2026). A malignant (clonal) proliferation of B- lymphocytes or T- lymphocytes which involves the lymph nodes, bone marrow and/or extranodal sites. "COX-2 and IL-32 protein expression was higher in 31 primary gastric B cell lymphoma patients compared to 19 chronic gastritis patients, especially so in patients who had HP-positive lymphomas; the expression level of COX-2 was positively correlated with the expression level of IL-32." (PMID 27398102, 2016).